MIR514B (microRNA 514b)
Synonyms: hsa-mir-514b; mir-514b
Gene: MicroRNA gene on chromosome X (147,250,151 to 147,250,230, reverse strand). Ensembl gene ENSG00000252583.
Homologues: Orthologues: chimpanzee MIR514B (100% identical), mouse Mir509 (76% identical), rabbit ocu-mir-506 (44% identical). Paralogues in human: MIR514A1 (81% identical), MIR514A2 (80% identical), MIR514A3 (80% identical), MIR509-1 (75% identical), MIR509-3 (72% identical), MIR513B (62% identical), MIR513A2 (59% identical), MIR507 (58% identical), MIR506 (54% identical).